TREM2 (triggering receptor expressed on myeloid cells 2)
Diseases named in the same sentence as TREM2 in open-access papers (continued):
Sharing a sentence is not in itself a finding about the gene and the disease.
tumor (continued). "By contrast, the number of tumor foci in the mice injected with TREM2 overexpressing MHCC97H cells was less than that in the control." (PMID 30683932, 2019). "Then we explored the underlying mechanism of decreased TREM2 expression in HCC using 50 cases of tumor and matched non-tumor tissues." (PMID 30683932, 2019). "Previous studies demonstrated that tumors exhibit a significant infiltration of immune cells, including myeloid cells expressing TREM2 during tumor initiation and progression." (PMID 31489935, 2019). "The results implied TREM2 knockdown markedly encouraged tumor growth, while TREM2 overexpression suppressed tumorigenesis." (PMID 30683932, 2019). "Weak TREM2 staining was seen in the tumor tissues, with strong TREM2 staining observed in the non-tumor tissues." (PMID 30683932, 2019). "After that we explored the upstream regulation mechanism of decreased TREM2 expression in HCC tumor tissues." (PMID 30683932, 2019). "We found that TREM2 overexpression suppressed tumor growth in vitro and in vivo via the negative regulation of the Wnt1/β-catenin signaling pathway." (PMID 31489935, 2019). "TREM2 expression in tumor tissues was found to be an independent prognostic factor of survival and recurrence." (PMID 30683932, 2019). "The injection of MC38-TREM2+DAP12 cells resulted in an approximately five-fold reduction in tumor volume compared with the injection of MC38-vector cells, implying that TREM2 overexpression dramatically suppressed tumor incidence." (PMID 31489935, 2019). "In the current study, we found that TREM-2 was up-regulated on peripheral blood monocytes in tumor-bearing host." (PMID 27102437, 2016). "In the current study, we found that TREM-2 expression was up-regulated in the tumor-bearing host while reduction of tumor burden led to the obvious decline of TREM-2." (PMID 27102437, 2016). "Mice in the TREM2-RNAi group and NC group were killed 36 days after inoculation, with average tumor weights of 0.17 ± 0.04 g and 0.42 ± 0.05 g, respectively (P < 0.0001)." (PMID 26506595, 2016). "We find that Trem2 deficiency synergizes with GPC3-CAR-T to enhance tumor control by expanding endogenous tumor-specific CD8+ T cells (not CAR-T amplification) and reeducating TAMs to an anti-tumor CXCL9hi/SPP1lo phenotype via metabolic reprogramming." (PMID 41564864, 2026). "Furthermore, therapies using Fc domain enhanced anti-TREM2 monoclonal antibody have been developed to promote anti-tumor immunity by eliminating and modulating TAM populations, which leads to enhanced CD8+ TIL infiltration and effector function." (PMID 40083710, 2025). "Different subsets of immunosuppressive TAMs (SPP1-C1Qa/b, proliferating, Nos2 glycolytic and OXPHOS TAMs) exhibited high expression of Trem2, Axl, Tim3 and Arg1, known markers of a pro-tumor phenotype, and were proportionally decreased in response to ACTM-838 treatment (except OXPHOS TAMs)." (PMID 41048107, 2025). "Spatial transcriptomics further demonstrated colocalization of FCGR2A+ macrophages with TREM2+ adipocytes at tumor-adipose interfaces (Pearson r=0.76, p=2.1×10-5), suggesting direct crosstalk between obese microenvironments and immunosuppressive myeloid populations." (PMID 41199823, 2025). "Additionally, TREM2 promotes tumor growth by impairing T cell-mediated immunity and immune escape from tumors in the TME." (PMID 40670983, 2025). "IL4I1 and TREM2 macrophage signatures were found in macrophages of the tumor microenvironment." (PMID 41342736, 2025). "The ALOX5AP inhibitor zileuton has been shown to decrease tumor-associated macrophage (TAM) infiltration in murine models, while targeting TREM2 and TYROBP may reverse immunosuppression." (PMID 40438577, 2025). "The identification of these TREM2/APOE/C1Q-positive macrophages not only offers a potential prognostic biomarker for ccRCC recurrence but also presents a promising target for therapeutic strategies aimed at preventing tumor relapse." (PMID 40083710, 2025).
tumor (continued). "In summary, TREM2+ TAMs are immunosuppressive, and TREM2 blockade restores anti-tumor immunity." (PMID 40821795, 2025). "In contrast, in a peripheral tumor model, subcutaneous injection of luciferase-labeled CT-2A cells (CT-2A-luc) resulted in significantly smaller tumor volumes in Trem2−/− mice, indicating that TREM2 may promote the growth of peripheral tumors." (PMID 40242752, 2025). "This drives a shift from the anti‐tumor CD5L+ phenotype to a pro‐tumor TREM2+ phenotype." (PMID 40552574, 2025). "For immune microenvironment remodeling, myeloid cell reprogramming therapies targeting organ‐specific markers like TREM2 and in situ tumor niche vaccine platforms may activate CNS anti‐tumor immunity." (PMID 40654157, 2025). "Also, TREM2+ TAMs were identified as pro-tumor cells as they promote GC cell proliferation and migration." (PMID 41253786, 2025). "In addition to physiological aging, it has been found that apolipoprotein E (APOE) secreted by tumor cells induces a subset of senescent neutrophils expressing the triggering receptor expressed on myeloid cells 2 (TREM2), which correlates with poor prognosis." (PMID 40860134, 2025). "Benefiting from the natural tumor-tropism of EcN and the enhanced permeability and retention (EPR) effect, scFv was packaged into OMVs and selectively delivered to hypoxic tumor regions, where it bound TREM2-expressing macrophages to alleviate immunosuppression." (PMID 41035884, 2025). "Like so, microglia, despite killing and phagocytizing tumor cells in the early stages of brain invasion, following the release of intrinsic factors, downregulate genes involved in phagocytic activity, such as Tmem119 or Trem2, switching from an anti-tumor phenotype to a pro-tumor phenotype." (PMID 40507830, 2025). "Additionally, TREM2+ TAMs can upregulate PD-L1 expression on VECs, hindering T cell extravasation through the vascular wall into the tumor nest." (PMID 40051497, 2025). "To further explore the impact of TREM2+ macrophages on CD8+ T cells in the tumor microenvironment, we intrahepatically injected Hepa 1–6 cells in combination with WT or Trem2−/− BMDMs into WT mice and then harvested liver tumors for single-cell sequencing at the experimental endpoint." (PMID 39838454, 2025). "Targeting TREM2 or IFITM limited MMRd tumor growth, but blocking IL1B was not beneficial." (PMID 40027748, 2025). "Thus, modulation of the TREM2 pathway by HTX is emerging as a novel and promising mechanism in the control of central nervous system tumor-associated inflammation, complementing its direct effects on tumor cells." (PMID 40864821, 2025). "In gliomas, knockdown of TREM2 expression in microglia may inhibit tumor cell proliferation and contribute to delaying tumor progression." (PMID 40028337, 2025). "Metabolic pathway analysis demonstrated pronounced dysregulation in TREM2+ macrophages, suggesting their metabolic reprogramming may fuel tumor progression." (PMID 40507339, 2025). "Next, to verify the effect of TREM2+ TAMs on GC growth, we depleted macrophages in mice using clodronate liposomes and subsequently administered siTREM2 BMDMs or scramble BMDMs following subcutaneous tumor formation." (PMID 41253786, 2025). "Among all the subclusters, the relative proportion of TREM2+ macrophages was much higher in tumor samples and metastatic lymph nodes, indicating that TREM2+ macrophages might serve as an important factor in ESCC metastasis." (PMID 39741182, 2025). "In the early stages, TREM2 limits inflammatory injury and tumor initiation." (PMID 39838454, 2025). "To verify whether TREM2+ macrophages regulate the expression of PKM, G6PD, and ALDOA in tumor cells, we detected their levels in Hepa 1–6 cells treated with CM from WT or Trem2−/− BMDMs." (PMID 39838454, 2025).
tumor (continued). "In addition, it would be interesting to further elucidate the roles of ceramide/TREM2 signal-derived bioactive mediators in the induction of exhausted CD8+ T cells within the primary tumor and other tissue microenvironments." (PMID 38302493, 2024). "Therefore, we then analyzed the function of tumor-infiltrating T cells and found that TREM2 inhibited T cell-mediated secretion of anti-tumor molecules, including granzyme B and perforin." (PMID 39135069, 2024). "Notably, the loss of Trem2 function in MΦs leads to increased IFN-γ-induced immune activation, a proinflammatory shift, and enhanced tumor-cell-killing capacity." (PMID 38279208, 2024). "Targeted treatment with anti-TREM2 monoclonal antibody can produce potent anti-tumor immune effects, inhibit tumor growth, and also enhance the anti-PD-1 immunotherapeutic response and improve the therapeutic effect of ICIs, making it an effective target for cancer immunotherapy." (PMID 38725629, 2024). "Moreover, tumor-infiltrating CD8+ T cells and NK cells in TREM2-deficient mice were more capable of secreting perforin and granzyme B, and GB1107 treatment further enhanced it." (PMID 39135069, 2024). "C1Q+TREM2+APOE+ TAMs detected in tumour stroma were proven to correlate with cancer recurrence." (PMID 38303024, 2024). "Concordant with their roles in tumor progression, the TREM2+ and UBE2C+ TAMs were abundant in PTs compared to NTs and MTs, which was concordant with their prognostic values for predicting poor survival of patients with primary liver tumors rather than metastatic liver tumors." (PMID 38414027, 2024). "Similarly, a humanized anti-TREM-2 mAb PY314 exhibited potent anti-tumor activity in mouse cancer models, but was ineffective in the clinical setting." (PMID 39737196, 2024). "However, TREM2 expression is significantly reduced with tumor progression, especially in metastatic HCC, and such reduction is associated with a poorer prognosis as well as aggressive pathological features." (PMID 38725629, 2024). "Compared to Mo detected in normal brains, Mo detected in PDOXs showed higher expression levels of genes associated with pro-tumorigenic TAMs (e.g., Cxcl13, Ctsd, Ccl4, Apoe) as well as Mg mimicry (e.g., Spp1, Trem2, Cst7, Tyrobp), further confirming an active crosstalk with tumor cells." (PMID 38566128, 2024). "Moreover, ECM-myCAF and TGFβ-myCAF colocalize with TREM2+ TAM and actively induce the TREM2+ TAM program to create an immunosuppressive area in the tumor bed." (PMID 38561380, 2024). "Moreover, immunosuppressive TREM2+ macrophages were recruited by tumour cells through the CCL15‐CCR1 axis to enhance immunosuppressive microenvironment and promote NAFLD‐related HCC progression." (PMID 37994257, 2024). "In addition, tumor-infiltrating immune cells analyzed by flow cytometry indicated that the proportion of M2-like macrophages was reduced in mice receiving TREM2 KO monocytes, whereas the proportions of CD8+ T and NK cells were elevated." (PMID 39135069, 2024). "Additionally, the interaction between TCR+ Macrophages and CD4+ T cells was most pronounced in tumor tissues from responsive patients, whereas that between TREM2+ Macrophages and CD4+ T cells was more intimate in tumor tissues from non-responsive patients." (PMID 38948071, 2024). "Besides, TREM2 is widely expressed on tumor cells and can regulate tumor cell proliferation and metastasis through various signaling pathways, thereby influencing tumor progression." (PMID 38725629, 2024). "Additionally, Trem2+ MΦs have been found to enhance NK cell activity and suppress tumor cell growth by modulating interleukin interactions and production in pathological conditions." (PMID 38279208, 2024). "However, in addition to SPP1+ and C1QC+ TAM populations, tumour-infiltrating monocytes have been identified and described as other cancer-specific moTAM subsets including TREM2+ TAM and IL-1β+ TAM." (PMID 39430099, 2024).
tumor (continued). "Over time, the expression of these inflammatory genes was rapidly declined, while the expression of factors that promoted tumor growth (such as Vegfa and Arg1 that promoted tumor angiogenesis, and the signature genes Trem2 and Apoe that promoted tumor growth) continued to rise." (PMID 39867913, 2024). "We noticed that almost all the tumour‐associated‐neutrophils (TAN), including neutrophil‐1 and neutrophil‐2, were presented in the tumours of branch two, and TREM2+macrophage and endothelial cell also had a higher proportion of infiltration comparing to that in branch one and three." (PMID 39021279, 2024). "Interestingly, further scRNA-seq from the sorted myeloid components of the tumor identified expression of Trem2, Cadm1, Folr2, and Mrc1, supporting that both TRM and recruited macrophage build the TAM pool." (PMID 39104525, 2024). "Furthermore, liquid chromatography-mass spectrometry identified that soluble galectin-3 secreted by tumor cells was a potential ligand for TREM2." (PMID 39135069, 2024). "While TREM-2 has been shown to promote an immunosuppressive environment that might support tumour growth, it also facilitates tissue repair and regeneration through anti-inflammatory pathways such as SYK, NF-kB, PI3K, AKT, and MAPK." (PMID 39684475, 2024). "Moreover, high levels of TREM2 are significantly correlated with the extent of tumor invasion, tumor-node-metastasis (TNM) stage, and histological grading." (PMID 38725629, 2024). "In addition to this, we also specifically highlight the expression levels of TREM2 in different tumor tissues, as well as the pathways by which TREM2 promotes or inhibits cancer progression." (PMID 38725629, 2024). "Notably, the relationship between TREM2 expression and various clinical phenotypes, such as tumor stage and patient survival, reinforces its potential utility in clinical assessments and personalized treatment planning." (PMID 39697329, 2024). "Blocking the specific ligands of TREM2 may be a major advancement in cancer immunotherapy and is expected to be a new target for tumor immunotherapy." (PMID 38725629, 2024). "However, in colorectal cancer (CRC) tissues, TREM2 expression decreases progressively with increasing tumor stage and plays a tumor-suppressive role in CRC." (PMID 38725629, 2024). "Notably, TREM2, as a major immune checkpoint on TAMs, has also been linked to depletion of CD8+ tumor-infiltrating lymphocytes (TILs) and anti-PD-1 resistance in human cancers." (PMID 38725629, 2024). "To summarize, TREM2 plays an important role in tumor progression and cancer immunotherapy, and targeting TREM2 may be an appealing target for immunotherapy." (PMID 38725629, 2024). "Indeed, we found that anti-TREM2 used in combination with neoAg SLP vax (initiated on day 12 post-transplant) enhanced efficacy in Y1.7LI tumor-bearing mice." (PMID 39446585, 2024). "Indeed, Detox-iCAF, IL-iCAF and IFNγ-iCAF recruit monocytes and induce a FOLR2+ tumor-associated macrophage (TAM) phenotype, while ECM-myCAF and TGFβ-myCAF promote TREM2+ TAM and NKG2A+ regulatory NK phenotypes." (PMID 38561380, 2024). "Furthermore, the expression level of TREM2 in tumor cells is also closely related to tumor progression." (PMID 38725629, 2024). "Therefore, more studies are needed in the future to verify the mechanism of TREM2’s regulatory effects on different tumor cells." (PMID 38725629, 2024). "TREM2 can also modulate tumorigenesis by affecting NK cell-mediated anti-tumor immunity." (PMID 38725629, 2024). "In contrast, SPP1+ or TREM2+ TAMs play an important role in the immune escape of the tumor cells." (PMID 38533207, 2024). "TREM2, FOLR2, and CD163 are all markers found on tumor-associated M2 macrophages in adult cancer and have been shown to suppress the immune response and promote tumor growth." (PMID 38358826, 2024).
tumor (continued). "Above all, by summarizing the role of TREM2 in cancer immunotherapy and the mechanism by which TREM2 regulates tumor progression, this paper clarifies TREM2’s role in both tumor progression and cancer therapy, identifying a new therapeutic target for oncology diseases." (PMID 38725629, 2024). "For example, the targeting of TREM2, SPP1 and MARCO is currently under extensive investigation, and the first in vivo studies demonstrated promising results associated with the inhibition of immunosuppression and further decreased tumor growth." (PMID 39516356, 2024). "Subsets of TAMs, such as TREM2+ TAMS, have recently been implicated in promoting an immunosuppressive TME and the simultaneous targeting of these cells in conjunction with aPD1 ICB enhances tumor clearance." (PMID 37164949, 2023). "This suggests that the ability to self-maintain in the tumor Is Trem2-dependent." (PMID 37164949, 2023). "In recent papers the role of TREM2 in cancer was elucidated showing that TREM2 is a marker of tumor-associated macrophages in cancers, that high expression of macrophage TREM2 correlates with poor survival, and that blocking TREM2 enhances anti-tumor response in mice." (PMID 36627355, 2023). "In comparison to non-cancerous colon mucosa (NM), CRC is significantly more infiltrated by CD163+ tumor-infiltrating macrophages (TAMs), including a fraction of immune suppressive TREM2+ macrophages; moreover, a significant reduction of CD3+CD4−CD8− double negative T lymphocytes occurs." (PMID 37370706, 2023). "Furthermore, we noted that a fraction of the TREM2+ cells were Ki67+, indicating active proliferation within the tumor (a point we will return to)." (PMID 37164949, 2023). "We also found that the tumor growth was more subdued in Trem2–/– mice than in wild-type mice." (PMID 37563723, 2023). "Additionally, TREM2 levels in peritumor macrophages positively correlate with tumor progression, while TREM2-positive myeloid cells exhibit strong inhibitory effects against the proliferation of T cells in vitro." (PMID 37563723, 2023). "As expected, the Trem2 locus displayed several open peaks across all samples, but there were some peaks specific to the inflamed wound and tumor context, arguing for the relationship between the tumor and wound environment." (PMID 37164949, 2023). "Furthermore, these observations highlight a potential direct tumor support mechanism beyond the known roles of TREM2+ macrophages in immunosuppression." (PMID 37164949, 2023). "Therefore, the genetic deletion (SiRNA) and pharmacological inhibition (blocking ApoEA interaction with TREM2) of these senescent-like MICs, including neutrophils suppresses tumor progression in different mouse models of prostate cancers." (PMID 37380989, 2023). "On the contrary, very recent evidence indicates that triggering receptor expressed on myeloid cells 2 (TREM2) confers a pro-tumorigenic program to macrophages that interferes with IL-15 release by tumor-infiltrating DCs, thus negatively affecting NK cell activity." (PMID 37298470, 2023). "Third, our study is incapable of answering how these circulating M-MDSCs from DLBCL patients express a higher surface TREM2, as upstream signals originating from the tumor site must play the key tune, and this warrants further investigation by bioinformatics analyses." (PMID 37029450, 2023). "Importantly, the modulation of the TREM2 pathway using blocking antibody remodeled the tumor myeloid landscape and enhanced anti-PD-1 therapy in a responsive tumor model." (PMID 37359522, 2023). "Furthermore, these results identify a direct mechanism to promote tumor proliferation, expanding the previously known functions of TREM2+ macrophages beyond immunosuppression." (PMID 37164949, 2023). "Trem2 deficiency or anti-Trem2 treatment improved ICI responses and reduces tumor burden." (PMID 37822933, 2023). "Modulating the TREM2 expression has been shown to alter tumor immunotherapy outcomes significantly." (PMID 38203185, 2023).